ALKBH5 (alkB homolog 5, RNA demethylase)
Diseases named in the same sentence as ALKBH5 in open-access papers (continued):
Sharing a sentence is not in itself a finding about the gene and the disease.
tumor (continued). "However, ALKBH5 knockout (KO) showed more dramatic effects in immune-complete (C57) mice than in immune-deficient (NSC) mice in suppressing tumor growth with a lower ratio of tumor volume (KO/NC)." (PMID 36566230, 2022). "Based on our findings, we propose that ALKBH5 plays an important supportive role in NSCLC tumor growth and metastasis." (PMID 41216500, 2026). "The results showed that ALKBH5 was down-regulated in tumor tissues compared with levels in matched normal tissues, while YAP was up-regulated." (PMID 41216500, 2026). "Elevated expression levels of ALKBH5 in OC promote tumour cell proliferation and migration and inhibit the autophagy process by increasing BCL-2 mRNA stability, which in turn activates the EGFR-PIK3CA-AKT-mTOR signalling pathway." (PMID 40356909, 2025). "The roles of both ALKBH5 and reader proteins in promoting tumorigenesis and development across many tumor types have established them as emerging novel therapeutic targets." (PMID 40958857, 2025). "Above all, the interaction mechanisms between ALKBH5 and reader proteins in genitourinary system tumors are summarized, providing novel insights for tumor treatment." (PMID 40958857, 2025). "Although FTO and ALKBH5 have oncogenic roles in the majority of cancers studied, they can also be tumor suppressors." (PMID 41373022, 2025). "HBx activates multiple tumor‐related genes, including ALKBH5 and MMP, through WDR5‐driven modification." (PMID 40060195, 2025). "For instance, ALKBH5 has the potential to influence the homeostasis of the tumor microenvironment by modulating macrophage polarization and function." (PMID 39904996, 2025). "Mechanistically, ALKBH5 modulates the tumor immune microenvironment and immunotherapy responsiveness through targeting TIM3." (PMID 40986143, 2025). "Second, developing more selective and pharmacokinetically favorable ALKBH5 inhibitors and investigating their immunomodulatory functions in tumor models." (PMID 41562066, 2025). "In mouse renal cell tumor models, the role of ALKBH5 in promoting tumor growth through the activation of tumor cells UPR and its relationship with MANF were investigated." (PMID 40603319, 2025). "Histological examination revealed that tumor cells expressing Alkbh5-WT had greater levels of methylated ALKBH5 than other groups." (PMID 39781264, 2025). "HL60/ADR cells with stable ALKBH5 downregulation were injected into nude mice to establish xenograft tumor models, followed by ADR treatment." (PMID 39465506, 2025). "Oppositely, ALKBH5 knockdown in PDO-816 acted synergistically with Oxaliplatin or 5-FU to suppress tumor growth and induce apoptosis." (PMID 41390849, 2025). "With the deep research on the regulatory mechanisms of m6A modification, there has been a growing focus on the functional ALKBH5 and reader proteins in tumorigenesis and tumor development." (PMID 40958857, 2025). "In murine models, silencing ALKBH5 not only inhibited tumor growth and metastasis but also promoted CD8+ T cell infiltration while reducing the proportion of Tregs and MDSCs, thereby reversing immune resistance via TME modulation." (PMID 41562066, 2025). "To effectively silence ALKBH5 gene expression, reverse tumor cell resistance, and enhance immunotherapy efficacy, we encapsulated ALKBH5 siRNA within the nanovesicles to obtain ALKBH5-siRNA-BNVs." (PMID 40585991, 2025). "Although current research is still at an early stage, accumulating evidence identifies ALKBH5 as a pivotal regulator of tumor immune responses and immunotherapy outcomes." (PMID 41562066, 2025). "Specifically, ALKBH5 influences tumor cell proliferation, invasion, and apoptosis by modulating the m6A modification status of key genes involved in tumor growth and metastasis." (PMID 40585991, 2025). "A higher proportion of epithelial/tumor cells expressed ALKBH5 (>30%) compared to stromal cells, myeloid cells, T cells, and B cells." (PMID 41390849, 2025).
tumor (continued). "ALKBH5 mRNA-loaded folic acid-modified exosome‒liposome hybrid nanoparticles restored its expression and significantly inhibited tumor progression in preclinical models." (PMID 40859309, 2025). "In NSCLC, ALKBH5 expression within tumor cells enhances the secretion of CCL2 and CXCL10, thereby recruiting PD-L1 + TAMs and promoting macrophage polarization toward the M2 phenotype." (PMID 40176140, 2025). "Taken together, these findings indicate that R283 ADMA or R316 SDMA of ALKBH5 can also lead to tumor development, which means that arginine methylation of ALKBH5 is vital for tumorigenesis." (PMID 39781264, 2025). "Depending on the cancer type, ALKBH5 has distinct behaviors, ranging from oncogene to tumor suppressor." (PMID 40603319, 2025). "Targeting of ALKBH5 by knockout or VNPs-siALKBH5 synergizes with chemotherapy to trigger tumor regression in CSCs-/PDOs-derived xenografts and ALKBH5 knockout mice." (PMID 41390849, 2025). "In tumor cells, ALKBH5 modulates the expression of chemokines, cytokines, and immune checkpoint molecules, thereby influencing immune cell infiltration and immune evasion." (PMID 41562066, 2025). "ALKBH5 overexpression removes m6A from HBx mRNA, increasing its stability and promoting tumor cell proliferation and migration." (PMID 40060195, 2025). "Up to now, the expression of ALKBH5 has been found to be up-regulated or down-regulated in various cancers and to play an oncogenic or tumor suppressive role in CRC and so on." (PMID 39781264, 2025). "The data clearly demonstrate that the tumor metastasis signals in the ALKBH5-siRNA-BNVs and NGR-ALKBH5-siRNA-BNVs groups were significantly lower than in the Control group." (PMID 40585991, 2025). "In summary, ALKBH5, a critical m6A demethylase, exerts complex and context-dependent roles in tumor immune regulation." (PMID 41562066, 2025). "This highlights the dual relevance of ALKBH5 in both inflammatory diseases and tumor immune evasion." (PMID 41562066, 2025). "Cells expressing Alkbh5-WT formed smaller tumors, and the tumor growth curve was slower than that of the vector group and ALKBH5-R317K group, which was consistent with the noticeably lower tumor weights." (PMID 39781264, 2025). "In conclusion, this study successfully utilized NGR-modified BNVs to deliver ALKBH5 siRNA, reversing immunotherapy resistance in OC, significantly inhibiting tumor growth and metastasis, and enhancing anti-tumor immune responses by modulating the TIME." (PMID 40585991, 2025). "In vivo results also demonstrated tumor xenografts shrinkage upon ALKBH5 overexpression, but this effect was weakened when FBXL5 was knocked down." (PMID 39680684, 2025). "In contrast, this review places greater emphasis on the immunoregulatory functions of ALKBH5 within the tumor immune microenvironment." (PMID 41562066, 2025). "As one of the major m6A demethylases, ALKBH5 has recently gained attention for its potential role in tumor immune regulation." (PMID 41562066, 2025). "This suppression leads to aberrant m6A RNA methylation that stabilizes JMJD8 and enhances PKM2 activity, promoting glycolysis and tumor progression, while restoration of ALKBH5 expression reverses these oncogenic effects." (PMID 41359051, 2025). "Taken together, systematically elucidating the multifaceted roles of ALKBH5 within the TME is essential for advancing our understanding of tumor immune regulation and for developing novel, precision-based therapeutic strategies." (PMID 41562066, 2025). "ALKBH5 has been reported to exert oncogenic or tumor suppressive function in a context-dependent manner." (PMID 41390849, 2025). "These EVs transferred circEML4 into tumor cells, where it interacted with ALKBH5, restricted its nuclear localization, and increased global m6A levels, thereby promoting malignant progression via the SOCS2/JAK-STAT pathway." (PMID 41562066, 2025).
tumor (continued). "HK2 can be directly mediated by the m6A modifiers METTL3, YTHDF1, IGF2BP2, FTO and ALKBH5 in colorectal cancer and cervical cancer, leading to increased glycolysis, upregulated aerobic respiration in mitochondria and tumor progression." (PMID 41373022, 2025). "Current research on ALKBH5 in tumor immunity has revealed its importance, but several limitations and unresolved questions remain." (PMID 41562066, 2025). "The upregulation of ALKBH5 inhibits this mechanism, possibly enabling tumor cells to evade programmed cell death and, thereby, fostering tumor growth." (PMID 39802639, 2025). "In this review, the mechanism of ALKBH5 interacting with reader proteins to regulate targeted gene expression and participate in tumor processes is summarized in different tumors based on the structure and function of ALKBH5 and reader proteins." (PMID 40958857, 2025). "Functional assays revealed that ALKBH5 overexpression attenuated the immunosuppressive capacity and tumor-promoting activity of MDSCs." (PMID 41562066, 2025). "Studies have reported that ALKBH5 plays a crucial role in regulating the immune response within the tumor microenvironment by controlling the levels of lactic acid and inhibitory immune cell accumulation." (PMID 40260303, 2025). "Previous reviews have primarily focused on the role of ALKBH5-mediated m6A modification in tumor progression." (PMID 41562066, 2025). "As a major m6A demethylase, ALKBH5 not only orchestrates tumor cell proliferation, migration, and metabolic reprogramming but also exerts profound effects on the tumor immune microenvironment (TME)." (PMID 41562066, 2025). "As a critical m6A demethylase, ALKBH5 profoundly influences the crosstalk between tumor cells and diverse immune cell subsets through modulation of RNA methylation dynamics." (PMID 41562066, 2025). "Particularly, the Treatment group, which received NGR-modified BNVs loaded with ALKBH5 siRNA alone, exhibited the most pronounced inhibition of tumor metastasis signals." (PMID 40585991, 2025). "A growing body of evidence suggests that demethylases, including ALKBH5 and FTO, are linked to the survival of cancer patients and the infiltration of immune cells within tumor tissues." (PMID 39987091, 2025). "Concordantly, 5-FU or Oxaliplatin in combination with ALKBH5 cKO most effectively inhibited cell proliferation, together with drastic down-regulation of β-catenin in tumor tissues." (PMID 41390849, 2025). "ALKBH5 has been employed in anti‐PD‐1 immunotherapy to regulate lactic acid levels in the tumor microenvironment (TME) and manage the accumulation of Tregs and myeloid‐derived suppressor cells (MDSCs)." (PMID 39802639, 2025). "This mini-review therefore focuses on the functional and mechanistic roles of ALKBH5 in tumor immune regulation." (PMID 41562066, 2025). "This regulatory axis is important in oncogenic contexts, where dysregulated ALKBH5 expression exerts context-dependent tumor-promoting or tumor-suppressing effects." (PMID 40986143, 2025). "ALKBH5 promotes the secretion of CCL2 and CXCL10, which recruit programmed death ligand 1-positive tumor-associated macrophages, promoting M2 macrophage polarization." (PMID 40585991, 2025). "This suggests that tumor cells are the predominant source of ALKBH5 in the CRC TME that corresponds to stemness properties." (PMID 41390849, 2025). "Increased expression of ALKBH5 restrains tumor proliferation, migration, and invasion, and inhibits tumor growth in vivo, a process intricately linked to period circadian regulator 1(PER1)." (PMID 39791162, 2025). "In a subcutaneous tumor formation model, ALKBH5 knockout significantly restricted the growth of tumors." (PMID 40603319, 2025). "Given its dual roles in promoting or suppressing antitumor immunity depending on tumor type and context, ALKBH5 emerges as both a potential biomarker and therapeutic target." (PMID 41562066, 2025).
tumor (continued). "Upon knockout of ALKBH5 in tumor cells, the Mct4/Slc16a3 pathway regulates lactic acid concentration and the accumulation of myeloid-derived suppressor cells (MDSCs) and regulatory T cells (Tregs) within the tumor." (PMID 40260303, 2025). "ALKBH5 silencing inhibited tumor growth (P < 0.01) and reduced the Ki67 positive rate in tumor tissues (P < 0.01)." (PMID 39465506, 2025). "In colorectal cancer, ALKBH5 promotes tumor progression by stabilizing RAB5A mRNA, correlating with poor patient survival." (PMID 41361128, 2025). "The results showed that, compared to the Control group, the ALKBH5-siRNA-BNVs and NGR-ALKBH5-siRNA-BNVs groups had significantly increased apoptosis in tumor tissues, confirming the efficacy of this treatment in inducing tumor cell apoptosis." (PMID 40585991, 2025). "We aimed to gain more insight into the connection between the abundance of tumor-infiltrating immune cells (TIICs) and the expression level of ALKBH5 in CRC cells." (PMID 39781264, 2025). "ALKBH5 facilitates hypoxia‐induced paraspeckle assembly and IL8 secretion to recruit tumor‐associated macrophages (TAMs) to promote GBM progression." (PMID 39974663, 2025). "Combinations of ALKBH5 cKO plus 5-FU or Oxaliplatin exhibited synergistic suppressive effects on tumor number and load." (PMID 41390849, 2025). "A pyrazolo and [1,5-a] pyrimidine derivative (DO-2728) increased the m6A level in AML cells by specifically downregulating ALKBH5, which eventually inhibited tumor growth." (PMID 40001461, 2025). "In this connection, ALKBH5 knockdown act synergistically with both chemotherapeutic drugs to suppress tumor growth and induce apoptosis in CSCs, validating ALKBH5 as a druggable target to reverse chemoresistance in CRC." (PMID 41390849, 2025). "Together, these findings reveal that ALKBH5 promotes immune escape and tumor progression through dual mechanisms: stabilizing PD-L1 in tumor cells and remodeling the TAM-driven immunosuppressive TME." (PMID 41562066, 2025). "Together, these gaps highlight the need for deeper mechanistic studies, improved models, and more comprehensive clinical validation to fully understand the role of ALKBH5 in tumor immunity." (PMID 41562066, 2025). "ALKBH5 has also been demonstrated to shape the tumor immune microenvironment by mediating the M2 polarization of macrophages and the immunosuppressive function of bone marrow-derived cells." (PMID 40001461, 2025). "Inhibition of ALKBH5 has been shown to enhance T cell infiltration and activation within the tumor, thereby strengthening the anti-tumor immune response." (PMID 39911396, 2025). "Decreased RNA m6A methylation promotes EMT and vasculogenic mimicry processes in GBM, with ALKBH5 upregulation or METTL3 downregulation driving increased tumor invasiveness." (PMID 40565099, 2025). "By delivering ALKBH5 siRNA to OC cells, the specific suppression of ALKBH5 expression can exert anti-tumor effects." (PMID 40585991, 2025). "For instance, studies have highlighted the significance of RNA methylation regulators like METTL3 and ALKBH5 in shaping tumor behavior by modulating m6A RNA modifications, providing promising avenues for BLCA treatment." (PMID 39991573, 2025). "In conclusion, this study successfully inhibited tumor metastasis in mice using NGR-modified BNVs loaded with ALKBH5 siRNA, leading to a significant reduction in tumor metastasis signals." (PMID 40585991, 2025). "ALKBH5 is an RNA demethylase enzyme that, upon inhibition, reduces the m6A modification levels in tumor cells, thereby affecting ITGB1 expression and inhibiting tumor cell proliferation and metastasis." (PMID 40585991, 2025). "In CRC and melanoma, ALK-04, an inhibitor of ALKBH5, can decrease the infiltration of immunosuppressive cells in the tumor microenvironment and suppress tumor growth." (PMID 38560499, 2024). "ALKBH5 protein expression in BC patient samples showed a range of staining in both the nuclei and cytoplasm of invasive tumour cells." (PMID 39127986, 2024).
tumor (continued). "Above all, our findings suggested that silencing MIR205HG inhibited tumor growth by downregulating JMJD2C/ALKBH5." (PMID 38252669, 2024). "The silencing ALKBH5 resulted in reduced tumor growth and invasion, while enhancing sensitivity to cisplatin, docetaxel, and 5-FU." (PMID 38544837, 2024). "As predicted, ALKBH5 knockdown decreased positive proportion of Ki67, indicating that ALKBH5 knockdown impaired tumour growth via inhibiting cell proliferation." (PMID 38098223, 2024). "Several recent studies reported that reduced ALKBH5 expression in BC cell lines decreased viability, migration, invasion and tumour growth and metastasis in mouse models." (PMID 39127986, 2024). "This evidence suggests that FTO and ALKBH5 are carcinogenic and tumor suppressor factors, respectively, in hypoxia." (PMID 39033180, 2024). "The observed patterns suggest a potential differential role of ALKBH5 in specific stages of tumor progression and the context of HBV infection." (PMID 38501918, 2024). "Suppression of YTHDF3 or ALKBH5 increases circ3823 expression, thus promoting angiogenesis, metastasis, and tumor growth." (PMID 39098905, 2024). "To clarify the role of ALKBH5 in controlling tumor growth and sensitivity to immunotherapy, we established an in vivo subcutaneous xenograft model." (PMID 38872221, 2024). "Collectively, the in vivo studies showed that ALKBH5 promotes cancer progression by facilitating tumor growth and maintaining an immunosuppressive microenvironment, whereas anti-PD-L1 therapy is more effective in tumors with high ALKBH5 expression." (PMID 38872221, 2024). "Research has shown that METTL14/ALKBH5 affects tumor growth and progression by regulating key cell cycle- and angiogenesis-related transcripts." (PMID 39295872, 2024). "Our analysis underscored the prevalence of ALKBH5 overexpression in numerous tumor types, including HCC, thus augmenting its potential role as a pan-cancer molecular marker." (PMID 38501918, 2024). "Akin to METTL3, ALKBH5 also influences the response to anti-PD-1 therapy by regulating lactate levels and the accumulation of suppressive immune cells within the tumor microenvironment." (PMID 39199429, 2024). "Another study also demonstrated that in immunocompetent C3H mice, ALKBH5 overexpression reduces tumor-infiltrating lymphocytes, which can be restored by IFNα treatment." (PMID 39199429, 2024). "Knockdown of ALKBH5 suppressed OV growth, colony formation, tumour formation and invasion, which were partially reversed by overexpression of PVT1." (PMID 38098223, 2024). "Based on this information, we explored the effect of the demethylating enzyme ALKBH5 on the anti-PD-L1 efficacy in NSCLC through the cross-talk of tumor cells and TAMs, hoping to shed further light on the role of m6A modification in immunotherapy." (PMID 38872221, 2024). "Targeting “erasers,” mainly FTO and ALKBH5, seems to primarily enhance PD-1 blockade therapy and inhibit tumor cells, being key to combined immunotherapy." (PMID 39372415, 2024). "In contrast, ALKBH5 functions as a tumour suppressor in thyroid cancer and Non‐Small Cell Lung Cancer (NSCLC) by reducing the expression of TIAM1 and YAP, respectively." (PMID 38545841, 2024). "In bladder cancer, ALKBH5 reduces CK2α in an m6A-dependent manner, which inhibits glucose uptake and sensitizes tumor cells to cisplatin." (PMID 38560499, 2024). "Recent studies have also shown that ALKBH5 is a novel tumor suppressor capable of inhibiting colon cancer invasion and metastasis." (PMID 38166832, 2024). "Taken together, these results suggest that the upregulation of HSPA4/ALKBH5/CD58 signaling axis in GC tumor cells negatively regulates the infiltration of CD8+ T cells in GC tumor mass." (PMID 38589927, 2024). "As shown in the consequence of the tumor subcutaneous implantation experiment, silencing of ALKBH5 effectively repressed tumor growth, as reflected by the significant decline of tumor size and weight compared to the negative control group." (PMID 38481816, 2024).